DPP4 (dipeptidyl peptidase 4)
Diseases named in the same sentence as DPP4 in open-access papers (continued):
Sharing a sentence is not in itself a finding about the gene and the disease.
diabetes (continued). "Certainly, DPP4 seems to exert many functions, both directly and indirectly, on cardiovascular districts, opening new possibilities of prevention and treatment of complications at this level, not only in patients affected by diabetes mellitus." (PMID 23853775, 2013). "Certainly, DPP4 seems to exert many functions both directly and indirectly on cardiovascular districts, opening new possibilities of prevention and treatment of cardiovascular complications not only in patients with diabetes mellitus." (PMID 23853775, 2013). "Molecular docking revealed that compounds 5, 8, 9, 14, 15 may be the major active ingredients of I. obliquus for the treatment of diabetes, and their antihyperglycemic effect may be mediated, at least in part, by inhibition of DPP-4 activity." (PMID 23325103, 2013). "DPP4 inhibitors are also effective in combination with several other diabetes drug classes." (PMID 22475049, 2012). "Although the definite cause was unknown, the Japan Association for Diabetes Education and Care (JADEC) released a “Recommendation” on 7 April 2010 to promote proper co-administration of a DPP-4 inhibitor and an SU." (PMID 24300302, 2012). "The Japan Association for Diabetes Education and Care (JADEC) released a recommendation in April 2010 to lower the dose of three major SUs (glimepiride, glibenclamide, and gliclazide) when adding a DPP-4 inhibitor." (PMID 24300302, 2012). "Dipeptidylpeptidase 4 (DPP4) inhibitors have clinical benefit in patients with type 2 diabetes mellitus by increasing levels of glucose-lowering incretin hormones, such as glucagon-like peptide -1 (GLP-1), a peptide with a short half life that is secreted for approximately 1 hour following a meal." (PMID 22475049, 2012). "Furthermore, the 2-azabicyclo[3.1.0]hexane derivative of 3-hydroxyadamantylglycine, named Saxagliptin, is a pharmaceutical of the dipeptidyl peptidase IV (DPP-4) inhibitor class against type 2 diabetes mellitus and entered the market in 2009." (PMID 22563360, 2012). "Placebo-controlled trials with Japanese diabetes patients have shown that DPP-4 inhibitors are not likely to cause hypoglycemia." (PMID 24300302, 2012). "GLP-1 receptor agonists are given preference over DPP-4 inhibitors in dual- and triple-therapy intensification regimens after metformin by the AACE and by the ADA/European Association for the Study of Diabetes as a tier-2 therapy when hypoglycaemia and weight concerns are paramount." (PMID 21355967, 2011). "Consequently, stable GLP-1 receptor agonists (Liraglutide, Exenatide), and DPP-4 inhibitors (Sitagliptin, Vildagliptin, Saxagliptin, Alogliptin) have been developed for the treatment of diabetes." (PMID 21673955, 2011). "We present here some of the key data on saxagliptin (SAXA) - a potent, selective DPP4 inhibitor - derived from abstracts presented at the 2010 meetings of the American Diabetes Association (ADA) and the European Association for the Study of Diabetes (EASD)." (PMID 21159194, 2010). "Additionally, emerging pharmacological interventions, such as GLP-1 receptor agonists, SGLT1/2 inhibitors, and DPP-4 inhibitors, offer promise not only for diabetes management but also for preventing cardiac remodeling and warrant further investigation for integration into perioperative care." (PMID 40002822, 2025). "DPP-4 inhibitory peptides have been identified in hydrolysates of fish skin, walnut, and milk proteins, suggesting that food-derived peptides may serve as promising natural agents for glucose regulation and diabetes prevention." (PMID 41517158, 2025). "The American Diabetes Association (ADA) guidelines include medications such as metformin, sodium–glucose cotransporter-2 inhibitors (SGLT2 i), glucagon-like peptide receptor agonists (GLP-1 RAs), dipeptidyl peptidase-4 inhibitors (DPP-4 i), thiazolidinediones, and sulfonylureas." (PMID 39858654, 2025).
diabetes (continued). "In light of the beneficial effects of DPP4 inhibition on metabolic disorders, including obesity and diabetes mellitus, we propose that DPP4‐GLP‐1/GLP‐1R may be a pivotal regulator of stress‐induced adipose inflammation and dysfunction via the negative modulation of the PI3K/AKT signaling pathway." (PMID 40742315, 2025). "Previous studies have shown that DPP4 inhibitors improve social interaction deficits and reduce depressive-like behaviors in various animal models of depression, including chronic restraint stress, chronic unpredictable mild stress, high fat diet, diabetes and morphine withdrawal." (PMID 40490517, 2025). "Consequently, oral semaglutide is expected to significantly reduce barriers to initiating GLP-1 RA therapy in individuals with diabetes and may lead to an increased transition from dipeptidyl peptidase-4 inhibitors (DPP-4is) to GLP-1 RA therapy." (PMID 40196376, 2025). "This type of combination of DPP4 inhibitors with metformin already exists on the market and has shown good control for diabetes, so the use of the extract with metformin could be useful for the treatment of diabetes." (PMID 40265815, 2025). "DPP-4 inhibitors could prevent adverse diabetes-induced myocardial remodeling." (PMID 38732142, 2024). "Moreover, it is crucial to evaluate whether DPP-4 inhibitors are more appropriate than other diabetes medications for DM1 patients, taking into account not only their potential benefits but also their cost-effectiveness." (PMID 39274465, 2024). "Within the subset of diabetes patients for which manual chart abstraction was performed, rates of medication use prior to hospitalization were as follows: insulin 50%, metformin 42%, DPP4 inhibitor 27%, sulfonylurea 14%, SGLT2 inhibitor 5.1% and GLP1 receptor agonist <1%." (PMID 39208154, 2024). "Thus, chronic hyperglycemia and accumulated AGEs may have affected the higher DPP4 activity in our diabetes subjects than in the healthy controls, who should exhibit lower AGEs." (PMID 39507187, 2024). "For individuals with diabetes, medications such as metformin, sulfonylureas, DPP-4 inhibitors, GLP-1 receptor agonists, SGLT2 inhibitors, and insulin may be prescribed to manage blood sugar levels and reduce the risk of cardiovascular complications associated with diabetes." (PMID 38756312, 2024). "Consequently, inhibiting DPP-4 is a crucial molecular target in the treatment of diabetes." (PMID 38667785, 2024). "A kidney biopsy was performed in a 64-year-old woman with type 2 diabetes mellitus and less than 1 g of proteinuria who rapidly progressed to end-stage renal failure after approximately 2 years of treatment with two dipeptidyl peptidase 4 (DPP-4) inhibitors for type 2 diabetes mellitus." (PMID 39135967, 2024). "The duration of diabetes mellitus (DM), blood pro-inflammatory markers, and dipeptidyl peptidase 4 (DPP4) activity are known predictors of diabetic kidney disease (DKD) progression in acute-onset type 1 DM (AT1DM) and type 2 DM." (PMID 39512972, 2024). "Therefore, in-depth studies are still warranted to identify the potential survival benefits associated with the usage of DPP4 inhibition in patients with or without diabetes mellitus and COVID-19." (PMID 36839456, 2023). "If DPP4 inhibitors prove effective in maintaining regulatory T cell distribution, they may potentially reduce rejection and foster transplant tolerance in patients with diabetes and chronic kidney disease who are taking these inhibitors." (PMID 38065905, 2023). "There is evidence that diabetes drugs targeting the enzyme DPP-4 can improve heart health, and researchers led by Hyoung Kyu Kim and Jong Chul Won at Inje University, Busan and Seoul, South Korea, evaluated one such drug, evogliptin, in a mouse model of diabetes." (PMID 37009790, 2023).
diabetes (continued). "Finally, we identified known drug targets for non-cardiac diseases, including those that have been associated with adverse cardiac outcomes (for example, ABCC1 (target of abiraterone for prostate cancer) and DPP4 (target of sitagliptin for pancreatic beta cells in diabetes))." (PMID 36950336, 2023). "DPP-4 inhibitors were observed to be related with a decreased incidence of HCC in individuals with Type 2 Diabetes Mellitus (DM) with chronic HCV or HBV infection in two Taiwanese studies." (PMID 38022651, 2023). "Based on this study, DPP-4 inhibitors may impair fertility in men with diabetes mellitus." (PMID 37893048, 2023). "We also confirmed whether changes in HbA1c levels affected BP onset, given that DPP4 inhibitors are antidiabetic agents that are used for type 2 diabetes mellitus treatment owing to their ability to reduce blood glucose levels by inhibiting the degradation of incretin peptides." (PMID 36685490, 2022). "Hence, DPP4 may be a potential drug target against AD and cognitive benefits in patients suffering from diabetes." (PMID 34880449, 2022). "The potential in diabetes treatment was evaluated through tests of free radicals neutralization, inhibition of lipid peroxidation process, and test of ferric ion reduction; activity in tests of inhibition of α-amylase, α-glucosidase and dipeptidyl peptidase-4 was also evaluated." (PMID 36432103, 2022). "Given that DPP4 inhibitors have been used as clinical therapies for diabetes (such as sitagliptin, saxagliptin, and vildagliptin), this study might shed light on the therapeutic potential of DPP4 inhibitors for preventing or attenuating SARS-CoV-2 infection in specific tumor patients." (PMID 33614513, 2021). "Thus our findings suggest that the inhibition of diabetes-induced DPP4 activity could be a plausible therapeutic strategy to reestablish glucose homeostasis in diabetes." (PMID 34043673, 2021). "Since DPP4 exhibits several pleiotropic effects not only by enzymatic but also by nonenzymatic pathways, DPP4 has been found to play an essential role in a variety of disease entities and states, such as inflammation, cancer, diabetes, hepatic, and renal fibrosis." (PMID 33514826, 2021). "Thus, the interaction between the SARS-CoV-2 spike protein and DPP4 could explain the link between COVID-19 and diabetes." (PMID 33562193, 2021). "However, the American Diabetes Association has not yet recommended DPP4 inhibitors as the first choice of hypoglycaemic agent for patients with DKD." (PMID 34950037, 2021). "In addition, our findings further reveal that the reversal of DPP4 expression in adipose tissue with non-diabetic plasma not only decreases plasma DPP4 activity and liver DPP4 expression but also ameliorates glucose intolerance and insulin resistance in diabetes." (PMID 34043673, 2021). "Hence, DPP4 inhibitors are widely used to treat type 2 diabetes mellitus patients." (PMID 33006264, 2021). "L.acaciae was thought to compact diabetes through its flavonoids, which are suggested to demonstrate powerful antioxidant activity, and act as inhibitors of biological targets, mostly enzymes such as α-glycosidase, α-amylase, and dipeptidyl peptidase IV (DPP-4)." (PMID 33572627, 2021). "In terms of its association with diabetes, there is increasing evidence of the positive effects of anti-diabetic drugs on psoriasis including glucagon-like peptide-1 (GLP-1) receptor agonists, dipeptidyl peptidase-4 (DPP-4) inhibitors, thiazolidinedione and biguanide." (PMID 33255783, 2020). "It was originally thought that some anti-diabetes treatment (such as metformin, PPARs, DPP4 inhibitors, GLP-1R agonists, SGLT2 inhibitors and insulin therapy) could influence the course of COVID-19; however, no convincing evidence has emerged to support this view." (PMID 33335527, 2020).
diabetes (continued). "Both glucagon-like peptide-1 (GLP-1) receptor agonist and dipeptidyl peptidase 4 (DPP-4) inhibitors enhance incretin levels, which inhibit glucagon release, which in turn, increases insulin secretion, as a class of oral hypoglycemics used to treat diabetes mellitus type 2." (PMID 32570738, 2020). "Since plenty of studies have shown that EGCG may have the potential to improve the glycemic profiles in patients with diabetes, we selected DPP4 protein as a receptor for molecular docking to study whether EGCG can imitate the action of DPP4 inhibitors with few side effects." (PMID 32104696, 2020). "The purpose of this study was to evaluate and compare the effects on laboratory parameters among monotherapy with five DPP-4 inhibitors in patients with type 2 diabetes mellitus (DM)." (PMID 32317005, 2020). "Therefore, we hypothesize that DPP4 might represent a link between diabetes and morbi-mortality/severity of COVID-19." (PMID 32848769, 2020). "Therefore, the inhibitors of DPP‐4 are widely used to treat diabetes." (PMID 32713161, 2020). "However, the mechanism by which DPP-4 inhibitors improve fatty liver in the presence of diet-induced obesity or diabetes remains unclear." (PMID 33105604, 2020). "Dipeptidyl peptidase-4 (DPP-4) inhibitors are used for the treatment of type 2 diabetes mellitus (DM)." (PMID 33051573, 2020). "Consequently, some diabetes patients may take a DPP4 inhibitor such as Sitagliptin to increase insulin secretion for diabetes therapy and ameliorate the therapeutic effect of GLP-1." (PMID 31652794, 2019). "The DPP4 inhibition potential of oxytocin offers new molecular insights and perspectives of oxytocin and cyclic peptides in general as lead to serine protease inhibitors and can be used as future therapeutics to reduce blood glucose levels and to manage diabetes mellitus." (PMID 31661941, 2019). "Some antidiabetic medications, including metformin, thiazolidinediones, dipeptidyl peptidase 4 inhibitors, and sodium/glucose cotransporter 2 inhibitor, have been shown to improve myocardial glucose uptake and contractile dysfunction in humans and in an animal model of diabetes." (PMID 31558158, 2019). "However, the effect of DPP-4 inhibitors on the cardiac (organ) dysfunction associated with sepsis (in the absence or presence of diabetes) has not yet been investigated." (PMID 30619349, 2018). "As the effect of DPP-4 inhibitors is glucose-dependent, it is quite possible that these drugs may not exert significant beneficial effect on β-cell function in subjects with well-controlled diabetes." (PMID 29970184, 2018). "While this is the first pharmacogenomic study of DPP-4 inhibitor treatment for diabetes in a Taiwanese population, the findings could provide some information on how genetic variants influence drug response and may benefit the development of personalized medicine." (PMID 28160554, 2017). "In addition, natural compound HCD and its successor MSN-HCD improved insulin resistance and promoted metabolism to control body weight as a valuable method, suggesting that they have the potential to develop as hypoglycemic drugs for diabetes therapy via DPP4 inhibition." (PMID 28498352, 2017). "Although the participants’ backgrounds including age, concomitant agents, and severity of diabetes differed between these studies, these findings suggest that DPP-4 inhibitors at least cause no harm to the vasculature and are useful for glycemic control in the usual clinical settings." (PMID 28490337, 2017). "In this study, we retrospectively investigated temporal changes in the renal function index of patients with type 2 diabetes mellitus (DM) and examined the influence of DPP-4 inhibitors on renal function." (PMID 29187821, 2017).
diabetes (continued). "Limited information about is available regarding DPP4’s functions in humans, with the exception that plasma DPP4 activity has been shown to be increased in inflammation-related metabolic disorders (including obesity and diabetes) and carotid arterial atherosclerosis onset." (PMID 27654253, 2016). "In addition, when recombinant DPP4 is added to adipocytes, it disrupts insulin-mediated phosphorylation of Akt suggesting that overexpression of DPP4 in conditions of obesity and diabetes may result in insulin resistance." (PMID 27213360, 2016). "One possibility could be the administration of glucagon-like peptide-1 receptor (GLP-1R) agonists or dipeptidyl peptidase-4 (DPP-4) inhibitors, two incretin-based therapies commonly used for the treatment of type 2 diabetes mellitus due to their effects on body weight reduction." (PMID 26828649, 2016). "Thus, further clinical research is required to investigate whether the observed vascular leakage after DPP4-inhibition in our study would actually lead to the aggravation of diabetic retinopathy in patients with diabetes." (PMID 27381080, 2016). "Similarly to the study presented here, a previous post-hoc analysis compared the two doses of canagliflozin (100 mg and 300 mg) with the dipeptidyl peptidase-4 (DPP-4) inhibitor sitagliptin (100 mg) in the attainment of diabetes-related QMs of glycemic control, BP, and body weight." (PMID 27495291, 2016). "Thus, DPP4 inhibitors may be strong candidates for medications used to manage diabetes in the immediate aftermath of a disaster as well as in the more remote period following the disaster." (PMID 25946187, 2015). "Similarly, we developed the therapeutic vaccine against DPP4 for diabetes mellitus." (PMID 26344893, 2014). "Therefore, it is anticipated that a combination of DPP-4 inhibitor and SU may synergistically stimulate insulin secretion and effectively ameliorate hyperglycemia in type 2 diabetes mellitus." (PMID 24578754, 2014). "Therefore, conventional anti-diabetic drugs such as sulfonylureas are not suitable because of the risk of prolonged hypoglycemia in these patients; recently approved DPP-4 inhibitors are used (with an appropriate dose reduction) in diabetes patients with severe renal impairment." (PMID 25526642, 2014). "In other words, whether DPP-4 itself is involved in vascular injury in diabetes remains unknown." (PMID 23984879, 2013). "Consequently, when incretin hormones are activated by DPP-4 inhibitors in the treatment of diabetes, not only do they act to lower blood glucose, they may also bring about various other changes in the body." (PMID 23024732, 2012). "In recent years, dipeptidyl peptidase-4 inhibitors (DPP-4i), widely prescribed for type 2 diabetes mellitus, have emerged as important pharmacologic triggers of BP." (PMID 42292723, 2026). "Background/Objectives: The objective was to analyze the effects of Dipeptidyl Peptidase-4 (DPP-4) inhibitors on glycemic control, insulin dose, and preservation of β-pancreatic function (C-peptide) in patients with type 1 diabetes mellitus (T1DM)." (PMID 41590243, 2026). "Type 2 diabetes mellitus (T2DM) is a complex and prevalent metabolic disorder, and dipeptidyl peptidase 4 (DPP4) inhibitors have proven effective, yet the identification of novel inhibitors remains challenging due to the vastness of chemical space." (PMID 40565043, 2025). "Current treatments for diabetes primarily include metformin, sulfonylureas, GLP-1 receptor agonists, DPP-4 inhibitors, and sodium-glucose cotransporter 2 (SGLT2) inhibitors." (PMID 40260393, 2025). "However, HbA1c levels were comparable between the groups(DPP-4 inhibitor group: 7.3±1.2% vs. Control: 7.4±1.1%, p=0.28), with nosignificant difference, suggesting that glycemic control at baseline was similarand minimizing the impact of diabetes severity on our findings." (PMID 40300646, 2025).